IL18 (interleukin 18)
Diseases named in the same sentence as IL18 in open-access papers (continued):
Sharing a sentence is not in itself a finding about the gene and the disease.
renal fibrosis (continued). "In the DOCA salt hypertension rat model, there was increased IL-18 expression, as a result of oxidative stress, on tubular epithelial cells accompanied by tubulointerstitial fibrosis; however, IL-18-/- mice experienced a significantly lower level of renal fibrosis and inflammation." (PMID 39595187, 2024). "A previous study reported that IL-18 blockade could ameliorate renal fibrosis and obstruction-induced epithelial-mesenchymal transition to protect against CKD in mice." (PMID 38730296, 2024). "Previous studies have shown that blocking IL-18 and IL-33 can improve renal fibrosis." (PMID 38152332, 2023). "This hypothesis is supported by the close correlation between IL-18 and adverse outcomes in this population and recent studies regarding M2 macrophage polarization and the development of renal fibrosis." (PMID 37384047, 2023). "Inhibition of IL-18 reduces renal fibrosis after ischemia/reperfusion." (PMID 36379914, 2022). "Macrophages are present in renal fibrosis and IL-18 is produced by macrophages." (PMID 36379914, 2022). "The inhibition of renal fibrosis by IL-18 deletion might be mediated via its suppression to the infiltration of infiltrated macrophages with different space-time special effect and phenotype specific features." (PMID 36379914, 2022). "The NLPR3 inflammasome and caspase 1 substrate IL18 have been found to mediate renal fibrosis." (PMID 33898439, 2021). "Taken together, these data indicate that the role of ASC in renal fibrosis is specific for IL-1β and IL-18, which are known to be processed by the inflammasome, though our evidence does not fully support the conclusion that this effect is inflammasome-dependent." (PMID 30057487, 2018). "Furthermore, by regulating inflammatory cell infiltration, the production of inflammatory cytokines and chemokines, and the conversion of bone marrow-derived M2-type macrophages into myofibroblasts, IL-18 plays a substantial role in the development of renal fibrosis after IRI." (PMID 40521043, 2025). "This study aimed to evaluate the relationship between urinary NGAL and IL-18 levels, two markers of kidney injury that have different characteristics, in experimental animal models with Uretero Pelvic Junction obstruction as a form of kidney injury with microscopic levels of renal fibrosis." (PMID 37363465, 2023). "Another study demonstrated that the neutralization of IL-18, a downstream cytokine of the inflammasome-dependent pathway of NLRP3, can prevent renal fibrosis after UUO in mice." (PMID 37685978, 2023). "NLRP3 is associated with renal fibrosis after UUO, whereas IL-1β, IL-18, and caspase-1 are not necessary for these pathways." (PMID 37685978, 2023). "IL-18 deletion reverted the overexpression COL-1 and renal fibrosis." (PMID 36379914, 2022). "Similarly, IL-18 neutralization ameliorated UUO-induced EMT and renal fibrosis." (PMID 30057487, 2018).
Hepatitis (29 papers, 2009 to 2025). Inflammation of the liver. "This phenotype is closely associated with abnormal activation of the NLRP3 inflammasome, a key driver of hepatitis that initiates inflammatory cascades through Caspase-1-mediated maturation of IL-1β and IL-18." (PMID 40868283, 2025). "Activated inflammasome initiates caspase-1 and determines IL-1β and IL-18 pro-inflammatory cytokines production, increasing liver inflammation, fibrosis, and damage in ADL and NAFLD." (PMID 38473721, 2024). "In AOSD, IL-18 is elevated in the serum, lymph node, skin eruptions, and synovial membranes, and the level of IL-18 is correlated with serum ferritin values, hepatitis severity, disease severity, and disease activity." (PMID 36072947, 2022). "In a previous study, adipose tissue-derived autologous MSCs-derived exosomes attenuated renal inflammation, decreased TNF-α, IL-6, and IL-1-β in the renal vein, and reduced the serum levels of TNF-α, IFN-γ, IL-6, IL-18, and IL-1β in a hepatitis model." (PMID 35279651, 2022). "Detection of IL-12, IL-18, and IL-21 levels was found to be helpful for evaluating the degree of liver cell damage and predicting the progression of hepatitis." (PMID 36383803, 2022). "The combination of IL-12, IL-18, and IL-21 levels was more helpful to evaluate the degree of liver cell damage and predict the progression of hepatitis." (PMID 36383803, 2022). "We also found that serum levels of IL-18 were significantly downregulated in response to local Ad-IL-18BP/IL-4 treatment in mice with hepatitis." (PMID 23516562, 2013). "NLRP3 inflammasome activates caspase 1 and promotes the maturation and secretion of downstream pro-inflammatory cytokines such as IL-1β and IL-18, resulting in the occurrence of programed cell death (apoptosis, autophagy, pyroptosis), liver inflammation and fibrosis." (PMID 37122694, 2023). "This may mimic events in vivo in which an inflammatory hepatic cytokine microenvironment, found in hepatitis or cancer, dominated by IL‐1, IL‐2, IL‐6, IL‐12, IL‐15, IL‐18, IFNα, IFNγ, and TNFα/β 38, 39, may lead to the expansion of CD49a+ NK cells." (PMID 28952190, 2018). "Upon sensing noxious signals, NLRP3 recruits pro-caspase-1 and the adaptor molecule ASC (apoptotic specklike protein-containing CARD), resulting in activation of caspase-1 as well as secretion of IL-1β and interleukin-18 (IL-18), which play a critical role in promoting liver inflammation." (PMID 29692782, 2018). "IL-4 and IL-18 are considered essential for the development of ConA-induced hepatitis." (PMID 23516562, 2013). "Therefore, in this study, we determined whether Aloe vera could attenuate liver injury in mice with APAP-induced hepatitis and also influence IL-12 and IL-18, which is a proinflammatory cytokines." (PMID 25005608, 2014). "Cd can activate the NLRP3 inflammasome, promoting liver inflammation and hepatitis, particularly severe during early estrus, by increasing TNF-α, MCP-1, and pro-inflammatory cytokines such as IL-1α, IL-1β, and IL-18." (PMID 39255638, 2024). "Overproduction of inflammatory cytokines such as IL-1β, IL-18, IL-6, and TNF-α during the activation of IRI-induced immune responses is referred to as liver inflammation." (PMID 35978104, 2022). "The locally activated macrophages in the liver produce a high amount of IL-18 and contribute to AOSD-related hepatitis." (PMID 34239943, 2021). "Therefore, miR-197 might be important for the reactivation of hepatitis by targeting IL18." (PMID 30717382, 2019). "In human studies, elevated IL-18 levels have been observed to correlate with mortality and mobility in patients with AKI, infections, SLE, hepatitis, and malignancies." (PMID 26496326, 2015). "Our previous study demonstrated that curcumin administration caused significantly elevated inflammatory mediators, IL-12 and IL-18 levels, in the serum of mice with APAP induced-hepatitis by using ELISA method." (PMID 25005608, 2014).
Hepatitis (continued). "Interestingly, Il18 gene expression was found to be suppressed in the HBV+DEN-treated liver, which warrants future investigations to determine its impact on hepatitis and HCC development." (PMID 40579434, 2025). "Of significance to the present study is that the levels of many cytokines (including IL-18, IFNs, TNF-α, IL-4 and TGF-β1) are elevated during hepatitis progression, and have been demonstrated to exhibit antiviral activity in both transgenic mice and cell culture systems." (PMID 19374779, 2009). "There might be a connection between IL-18 levels and chronic hepatitis in stable hemodialysis patients (IL-18 levels with vs. without hepatitis: 1172.39±862.28 vs. 731.64±550.49 pg/ml, p = 0.01)." (PMID 24599060, 2014). "The transcriptomic profile of 284 genes involved in inflammation, cell signaling, and remodeling showed that the expression of IL-1 family members, IL-1α, IL-1β, and IL-18, was not varied between WT and IL-33 KO mice following L2-MHV3 hepatitis." (PMID 28607531, 2017). "However, the effect of Aloe vera on inflammatory mediators, IL-12 and IL-18, in animal models with APAP-induced hepatitis has never been investigated." (PMID 25005608, 2014). "However, the effect of Aloe vera on IL-12 and IL18, in mice with APAP-induced hepatitis has never been investigated." (PMID 25005608, 2014).
Anxiety (28 papers, 2006 to 2026). Intense feelings of nervousness, tension, or panic often arise in response to interpersonal stresses. "Increased IL-18 concentrations in limbic structures such as the amygdala and hypothalamus are associated with intensified anxiety and depressive responses." (PMID 41008651, 2025). "Cytokines IL-1β and IL-18 promote neuronal hyperreactivity in the basolateral and central amygdala, enhancing fear and anticipatory anxiety responses and hindering the extinction of fear memory." (PMID 41008651, 2025). "In numerous animal models, MCC950 has been shown to reduce IL-1β and IL-18 levels in the hippocampus and amygdala, decrease microgliosis, and reverse anhedonia, depressive, and anxiety-like behaviors." (PMID 41008651, 2025). "It not only increased the concentrations of cytokines, including IL-1β and IL-18, in the PFC and HC, but also caused anxiety- and depressive-like behaviors." (PMID 36747075, 2023). "The positive link with IL-18 is further supported by elevated levels of IL-18 in anxiety including increased levels with severity, indicating clinical implications." (PMID 35082268, 2022). "Basal CRP, IL-6 andTNF-α, as well as most individual LPS-stimulated inflammation markers (IL-6,IL-8, IL-10, IL-18, MCP-1, MIP-1α, MIP-1β, MMP2 and TNF-β) weresignificantly associated with depressive and anxiety symptom severity." (PMID 27244234, 2016). "Results indicated that intranasal dantrolene nanoparticle treatment robustly inhibited LPS-induced increases in depressive and anxiety behavior, LPS-induced pathological elevation of IL-1β and IL-18 levels in the blood and brain, and LPS-induced activation of pyroptosis." (PMID 41633971, 2026). "Activated caspase-1 cleaves Pro-IL-1β and Pro-IL-18 into their active forms, IL-1β and IL-18, thereby stimulating hippocampal inflammatory cells, exacerbating inflammation, promoting the formation of neurotoxic A1 astrocytes, and inducing depressive-like behaviors such as anxiety and despair." (PMID 39114351, 2024). "Similarly, prenatal restraint stress increases the level of IL-18 in the hippocampus of male and female rat offspring, as well as levels of anxiety-related and depression-related behavior, impaired recognition memory, and diminished exploration of novel objects compared to control rats." (PMID 37566022, 2023). "Therefore, our results suggested that Il18−/− mice might exhibit behavioral changes including heightened anxiety in response to acute restraint stress because of decreased stress tolerance, and they may be regarded as a diathesis-stress model." (PMID 36151082, 2022). "Thus, we hypothesized that while IL-18 is key in adaptive homeostatic regulation of normal neuronal functions in amygdala, it also contributes to the development of maladaptive stress-induced AUDs and anxiety." (PMID 37566022, 2023). "Unlike basal inflammation, LPS-stimulated inflammation was stillassociated with (anxiety) symptom severity after adjustment for lifestyle and health(IDS: IL-8, MCP-1, MMP2; BAI: LPS index, IL-6, IL-8, IL-10, IL-18, MCP-1, MMP2,TNF-β)." (PMID 27244234, 2016). "One of the key factors involved in this process is interleukin-18 (IL-18), a pro-inflammatory cytokine whose levels are elevated in individuals suffering from PTSD and correlate with the severity of anxiety symptoms, cognitive function deficits, and impaired emotional regulation." (PMID 40806635, 2025). "Moreover, the positive association of PRS-ANX with IL-18 and a negative association with sIL-2R as robust marker of T-cell activation could implicate that innate and adaptive immunity may differently affect anxiety." (PMID 35082268, 2022). "The concentrations recorded for the IL-18 in plasma and saliva did not correlate with anger and anxiety scores." (PMID 29445205, 2018). "Moreover, IL-18 regulates motor activity, anxiety, and spatial learning without affecting synaptic plasticity." (PMID 29147584, 2017).
Salmonella Infections (28 papers, 2009 to 2025). Infections with bacteria of the genus SALMONELLA. "In order to unravel the causal relationship between IL-18, IFNγ and infection outcome, we reconstituted IL-18 and IFNγ in stopΔIEC mice and compared their susceptibility at early time points (18 hpi) of Salmonella infection." (PMID 32330185, 2020). "Within the first 36 h after Salmonella infection the Naip/NLRC4 inflammasome is required for Caspase-1 mediated cell extrusion associated with IL-18 production whereas at a later time point (>72 h post infection) non-canonical inflammasome activation involving Caspase-11 is needed." (PMID 34497340, 2022). "Interestingly, in vivo IL-18 neutralization causes a marked decrease in circulating IFN-γ levels during Salmonella infection." (PMID 25115174, 2014). "During enteric Salmonella infection, the activation of caspase-1 and the production of IL-1β and IL-18 provide a protective host response." (PMID 38396532, 2024). "Treatment of mice with IL-18 neutralizing antibody resulted in a concomitant decrease in cecal shedding during Salmonella infection." (PMID 32330185, 2020). "Our work uncovers a critical role for vitamin A in coordinating a biphasic immune response to Salmonella infection by regulating IL-18 production by IECs." (PMID 32330185, 2020). "Activation of IL12b:IL18➔ IFN-γ axis is one of most important mechanisms in the fight against Salmonella infection." (PMID 25162711, 2014). "ENSGALG00000048475, FLNA, MYL10, and IL18 were enriched in terms of Salmonella infection." (PMID 37761904, 2023). "Other investigators also showed that caspase-4/11 in intestine epithelial cells could act independently of NLRP3 to directly process IL18 and induce pyroptosis during Salmonella infection." (PMID 36436756, 2023). "In addition, the Casp1-/—, IL-1β-/—, and IL-18-/—mice also succumbed to Salmonella infection more rapidly than wild-type (WT)-C57BL/6 mice, with markedly higher bacterial burdens in spleens, Peyer’s patches, and mesenteric lymph nodes." (PMID 37155697, 2023). "This host defense mechanism relies in part on IL-18 signaling to intestinal goblet cells and promotion of their AMP expression, regulating both mucosa-associated microbiome composition and protection against Salmonella infection." (PMID 33542493, 2021). "We hypothesized that RAR signaling in IECs modulates cell death response during Salmonella infection via IL-18." (PMID 32330185, 2020). "It was reported that Salmonella infection stimulated pyroptosis of macrophages, a newly identified program of caspase-1-correlated cellular demise, resulting in cell lysis with release of IL-1β and IL-18." (PMID 26811498, 2016). "The model predicts that Casp11 induced cell death in the absence of Casp1-dependent IL-1B and IL-18 production increases host susceptibility to Salmonella infection." (PMID 23977202, 2013). "The initial stages of Salmonella infection are characterized by effective recruitment and activation of phagocytes, partly due to a massive inflammatory response in infected tissues, including the expression of inflammatory cytokines [e.g., IL-6, IL-12, and IL-18]." (PMID 36361621, 2022). "This suggested that IL-18 may also play a protective role against Salmonella infections." (PMID 21637513, 2009). "Consistent with our findings with disulfiram, we observed a significant decrease in IL-1 and IL-18 release in GSDMD-/- THP-1 macrophages compared to WT THP-1 macrophages following Salmonella infection." (PMID 40162563, 2025). "IL-18 is vital in stimulating Th1 cells to release IFN-γ, which plays a critical role in macrophage activation for the control of persistent salmonella infection." (PMID 34887848, 2021). "Our results in stopΔIEC mice demonstrated a direct correlation between intestinal IL-18 levels, RAR signaling, IFNγ production and resistance to Salmonella infection." (PMID 32330185, 2020).
Salmonella Infections (continued). "In salmonella infection pathway, IL8 and IL18 genes down-regulated the expression of through MAPK-AP-1 pathway." (PMID 29410628, 2018). "Pro-inflammatory cytokines such as interleukin (IL)-6, IL-1β (also called IL-1 F2), IL-18 and tumor necrosis factor (TNF)-α are released during early Salmonella infection." (PMID 25115174, 2014). "Recent studies with enteric Salmonella infections concluded that enterocyte IL-18 was not required for bacterial control, but rather that neuronal IL-18 was important and that expression of NLRP6 and ASC in neurons was likely involved in this response." (PMID 33372132, 2021). "Moreover, TLR2, TLR4, TLR7, and IL8 were enriched in Toll-like receptor pathway, IL8 and IL18 were enriched in the NOD-like receptor pathway, and TLR4, IL8, and IL18 were enriched in the salmonella infection pathway." (PMID 29410628, 2018). "Similarly, REV infection would destroy the immune defense of lymphocytes through MAPK-AP1 via Toll-like receptor-, NOD-like receptor-, and salmonella infection pathways to reduce the secretion of IL8 and IL18." (PMID 29410628, 2018). "Considered to the function of TLR2, TLR4, TLR7, TNF2, IL8, and IL18, it was revealed that the immune defense would been inhibited for REV infection through salmonella infection, NOD-like receptor, Toll-like receptor and MAPK-AP1 pathways." (PMID 29410628, 2018). "The combined effect of OMWW-EP on IL-18, which induced gene expression and reduced cytokine release (without Salmonella infection), leads the authors to suppose that this is the pathway through which OMWW-EP potentially protects IPEC-J2 cells against S. typhimurium infection." (PMID 38396532, 2024). "Studies in the mouse indicate that αβ-T cells are not required during the first week of Salmonella infection and IFNγ is produced in response to IL12 and IL18 in rag−/− and SCID mice that lack T cells." (PMID 21048923, 2010).